ADH1B (alcohol dehydrogenase 1B (class I), beta polypeptide)
Diseases named in the same sentence as ADH1B in open-access papers (continued):
Sharing a sentence is not in itself a finding about the gene and the disease.
Hypertension (8 papers, 2015 to 2024). The presence of chronic increased pressure in the systemic arterial system. "Similarly genetic epidemiological studies focusing on genetic variants (rs671/rs1229984) within the aldehyde/alcohol dehydrogenase (ALDH2/ADH1B) gene demonstrated that individuals carrying the risk allele for alcohol consumption had a higher risk of hypertension and CVD compared to non-carriers." (PMID 35885821, 2022). "Subset analysis among the 182 patients with lone AF and 914 controls (control II) (<60 years of age and without hypertension), both ALDH2 and ADH1B SNPs were significantly associated with AF (P = 0.013, OR = 0.7; P = 0.0007, OR = 1.4, respectively)." (PMID 27927211, 2016).
Insulin resistance (7 papers, 2015 to 2025). Increased resistance towards insulin, that is, diminished effectiveness of insulin in reducing blood glucose levels. "This study investigates the relationships between ADH1B gene rs1229984 mutation, alcohol consumption, gut microbiota, and insulin resistance." (PMID 40871697, 2025). "A recent study indicated that ADH1B is involved in the metabolic activity of adipose tissues that is associated with insulin resistance." (PMID 36923554, 2022). "This is the first report demonstrating that Adh1b is also upregulated in glomeruli, indicating a direct association with insulin resistance and suggesting that metabolic stress may directly influence glomerular gene expression profiles." (PMID 40806550, 2025). "Our study suggested a gene–alcohol interaction on gut microbiota and potentially different roles of alcohol-related gut microbiota in the links between alcohol consumption and insulin resistance between the ADH1B variant carriers and non-carriers." (PMID 40871697, 2025). "Our findings also suggest a potential role of gut microbiota in the protective association between alcohol consumption and insulin resistance in the ADH1B variant non-carriers." (PMID 40871697, 2025). "We constructed a microbiome score based on alcohol-associated microbiota in the ADH1B non-carriers and found that higher levels of alcohol consumption were associated with lower odds of insulin resistance only in individuals with lower microbiome scores but not those with higher microbiome scores." (PMID 40871697, 2025). "Another interesting finding of our study is that gut microbiota associated with alcohol consumption in the ADH1B non-carriers might modify the relationship between alcohol consumption and insulin resistance." (PMID 40871697, 2025). "However, to the best of our knowledge, no studies have examined the relationship between alcohol consumption and gut microbiota according to host ADH1B genotypes, and how this may relate to insulin resistance is largely unknown." (PMID 40871697, 2025). "Furthermore, our individual species analysis identified several gut bacterial species which might modify the association between alcohol consumption and insulin resistance in the ADH1B non-carriers." (PMID 40871697, 2025).
pancreatic cancer (7 papers, 2011 to 2025). "Our study also demonstrated the effect of ADH1B rs1229984 on the risk of pancreatic cancer, especially the CC genotype." (PMID 35670037, 2023). "The major strength of the current study is that it is one of the few studies that assessed the combined impact of ADH1B and ALDH2 polymorphisms on the association between alcohol use and pancreatic cancer." (PMID 34267279, 2021). "In addition, existing studies indicated that ADH1B has a good prognostic significance for pancreatic cancer as well." (PMID 36523602, 2022). "In conclusion, our study did not support an association between alcohol use and pancreatic cancer even after considering the level of alcohol use and the influence of ADH1B and ALDH2 polymorphisms." (PMID 34267279, 2021). "Consistent with that study, our results also showed no independent association between the polymorphisms of ADH1B and ALDH2 and pancreatic cancer risk." (PMID 34267279, 2021).
Cirrhosis (6 papers, 2016 to 2024). A chronic disorder of the liver in which liver tissue becomes scarred and is partially replaced by regenerative nodules and fibrotic tissue resulting in loss of liver function. "Carriage of GSTM1 null and rs2066701CC genotype of ADH1B were found to be associated with increased risk of progression of ALC to decompensated cirrhosis." (PMID 26937962, 2016). "Furthermore, variants associated with cirrhosis trough alcohol consumption were found in alcohol dehydrogenase 1B (ADH1B), genes involved in de novo lipogenesis and retinol metabolism." (PMID 38662298, 2024). "Additionally, certain Asian populations with genetic polymorphisms in ALDH1 and ADH1B have a higher risk of cirrhosis, further contributing to the burden of cirrhosis in the Asia-Pacific region." (PMID 37647379, 2023). "Among the 20 NAFL and cirrhosis variants, only p.Cys130Arg in APOE and p.His48Arg in ADH1B were associated with BMI (nBMI measures = 486, 305)." (PMID 36280732, 2022). "The cirrhosis effects were proportional to the PDFF effects except for p.His48Arg in ADH1B (alcohol dehydrogenase 1b) and p.Cys282Tyr in HFE (homeostatic iron regulator)." (PMID 36280732, 2022).
ischemic stroke (6 papers, 2015 to 2024). A stroke disorder caused by obstruction of blood flow to the brain, due to thrombotic (local blood clot formation) or embolic (due to a blood clot or other material traveling from another site) event. "Although previous studies have evaluated the interaction between alcohol drinking and ADH1B and ALDH2 variants, they mainly focused on ischemic stroke and ALDH2 rs671." (PMID 34051793, 2021).
alcoholic liver diseases (5 papers, 2015 to 2024). A disorder caused by damage to the liver parenchyma due to alcohol consumption. "In a recent study we demonstrated that Japanese alcoholic men with the ADH1B*2 allele had lower BMIs, lower blood ethanol levels in the morning after drinking the day before, and a higher prevalence of advanced alcoholic liver disease than Japanese alcoholic men with the ADH1B*1/*1 genotype did." (PMID 26284938, 2015). "Among the top 30 genes in the gene regulatory network, 7 genes are enriched in alcoholic liver disease (hsa04936), including TNF, IL6, IFNA1, CYP2E1, ALDH2, ADH1B, ADH1C." (PMID 38429802, 2024).
asthma (5 papers, 2012 to 2025). "We showed that four genes are genetically associated with asthma or asthma-related phenotypes (the AGC1 gene associated with atopy and atopic asthma, the IFI6, ADRA2A and ADH1B genes associated with asthma)." (PMID 23148572, 2012). "The rs11630178 in the AGC1 gene is associated with atopy (p=0.0003) and atopic asthma (p=0.0001), the rs1247653 located in the IFI6 gene (p=0.019), the rs1119529 in the ADRA2A gene (p=0.009) and the rs13103321 in the ADH1B gene (p=0.002), are associated with asthma." (PMID 23148572, 2012). "Therefore, the ADH1B gene seems to be involved in an increase of airway obstruction in asthma by its effects on the alcohol metabolism." (PMID 23148572, 2012).
Cognitive impairment (5 papers, 2014 to 2025). Abnormal cognition is characterized by deficits in thinking, reasoning, or remembering. "The KSS-2 will determine how the genotypes (e.g., ALDH2, ADH1B, and APOE), SVD burden, and/or lifestyle factors interact with cognitive impairment, cerebral cardiovascular disease, and death." (PMID 40603063, 2025). "We examined the associations of four single nucleotide polymorphisms (SNPs) on aldehyde dehydrogenase (ALDH) and alcohol dehydrogenase (ADH) genes (i.e., ALDH2 rs671, ADH1B rs1229984, ADH1B rs1042026, and ADH1C rs1693482) and cognitive impairment among the oldest-old." (PMID 35368830, 2021).
diabetes (5 papers, 2010 to 2022). "It is conceivable that the associations between cardiovascular risk factors including lipid profile, BMI, and diabetes and the ADH1B and ALDH2 genotypes in Japanese alcoholics modify their risk of cardiovascular events." (PMID 26284938, 2015). "The ADH1b fast metabolizing AA genotype also seemed to increase the risk of IGT/diabetes compared to the GG and GA genotypes." (PMID 20700531, 2010). "The ADH1B and ALDH2 gene polymorphisms in Japanese alcoholics modify cardiovascular risk factors such as weight gain, hypertension, and diabetes mellitus; therefore, these polymorphisms may play an indirect role in the development of cardiovascular diseases." (PMID 26284938, 2015). "Significant interactions were observed between alcohol and ADH1b (rs1229984) with respect to LDL and between alcohol and ALDH2 (rs886205) with respect to IGT/diabetes." (PMID 20700531, 2010).
liver cancer (5 papers, 2021 to 2025). An epithelial or non-epithelial malignant neoplasm that arises from the liver. "For liver cancer, there was a null estimate overall (OR 1.40, p = 0.10), but a nominally significant positive estimate in Million Veteran Program and when using the ADH1B-rs1229984 variant." (PMID 41398582, 2025). "Moreover, we found evidence supporting a harmful effect of alcohol consumption on liver cancer in the analysis utilizing the ADH1B-rs1229984 genetic variant only." (PMID 41398582, 2025). "Similarly, in our study we found clear inverse associations of the ADH1B‐rs1229984 A‐allele with risks of overall and IARC alcohol‐related cancers, mainly driven by UADT cancers and potentially also by liver cancer, but there were no clear associations with other cancer sites." (PMID 35048370, 2022).
liver disease (5 papers, 2007 to 2025). "Genetic polymorphisms in ALDH2 and ADH1B are key determinants of individual alcohol sensitivity and are significant in the progression and natural history of liver disease." (PMID 40943250, 2025). "Among those participants who were alcohol dependent, ADH1B*3 was associated with significantly higher levels of the liver enzyme aspartate aminotransferase, which can be indicative of alcohol-induced liver disease." (PMID 17718398, 2007). "Genetic polymorphisms in ALDH2 and ADH1B significantly influence alcohol metabolism and the accumulation of toxic metabolites, thereby determining the risk of various alcohol-related diseases, including liver disease." (PMID 40943250, 2025). "The severity of liver disease may at least in part account for the suppressive effects of the ADH1B*2 allele on serum HDL-C and LDL-C levels." (PMID 26284938, 2015). "We have proposed the hypothesis that CYP2E1 activity is more strongly induced by ADH1B*2-associated fast ethanol metabolism in alcoholics, because this hypothesis explains all of the ADH1B-associated differences in BMI, alcohol metabolism, and the prevalence of advanced liver disease." (PMID 26284938, 2015). "Alcohol dehydrogenase 1B (ADH1B) and aldehyde dehydrogenase 2 (ALDH2), members of the alcohol dehydrogenase family, have important roles in liver diseases." (PMID 35237626, 2022). "It would be better to sequence the whole genome of ADH1B and ALDH2 to discover new loci that might play significant roles in the pathogenesis of CHB or other HBV-related liver diseases." (PMID 35237626, 2022).
oesophageal cancer (4 papers, 2013 to 2022). "Two genetic variants that alter alcohol metabolism, ALDH2‐rs671 and ADH1B‐rs1229984, can modify oesophageal cancer risk associated with alcohol consumption in East Asians, but their associations with other cancers remain uncertain." (PMID 35048370, 2022). "Previous studies have shown that the ALDH2‐rs671 AA and ADH1B‐rs1229984 AA and AG genotypes were associated with lower oesophageal cancer risk compared to the GG genotype, and that ALDH2‐rs671 genotype may modify the relationship between alcohol intake and oesophageal cancer risk." (PMID 35048370, 2022). "The associations of ADH1B‐rs1229984 with overall cancer, IARC alcohol‐related cancers and oesophageal cancer were directionally consistent across different drinking groups, and were more apparent among ever‐regular drinkers." (PMID 35048370, 2022). "ADH1B and AOX1 are involved in the metabolism of nicotine, with the former gene implicated in the risk of esophageal carcinoma." (PMID 24134934, 2013). "We found that the slow-acting ADH1B variant also increased the risk for oesophageal cancer, regardless of ALDH2 variant." (PMID 26229204, 2015).
type 2 diabetes (4 papers, 2020 to 2022). "The authors found that two putative APCs populations, which are termed hP1 in subcutaneous and hP4 in visceral adipose tissue and express GPX3, ATF3 and ADH1B, are associated with the Type 2 diabetes (T2D) status." (PMID 34935088, 2022). "In particular, the alcohol-raising allele of the ADH1B variant was strongly associated with an increased risk of type 2 diabetes." (PMID 32895727, 2020). "We found that the ADH1B gene is a missense mutation annotated by the variant rs1229984 associated with alcohol consumption, which implied that it may be a key gene in the biological mechanism of alcohol consumption and type 2 diabetes." (PMID 34830198, 2021). "In addition, rs1229984 in the ADH1B gene, which is robustly associated with alcohol consumption and explains the majority of the variance of alcohol consumption, was positively associated with type 2 diabetes (OR 1.57 [95% CI 1.20, 2.07])." (PMID 32895727, 2020).
adenoma (3 papers, 2022 to 2023). A neoplasm arising from the epithelium. "Decrease/loss of ADH1B in MFs during the adenoma-carcinoma sequence contributes to disruption of the retinol-mediated suppression of tumor-promoting inflammation in CRC and to the increase of IL-6 in neoplastic tissue." (PMID 37185128, 2023). "A lower expression of ADH1B at the mRNA level was also observed in adenomas compared with adjacent normal mucosa." (PMID 36923554, 2022).
alcoholic liver cirrhosis (3 papers, 2016 to 2025). A disorder of the liver characterized by the presence of fibrotic scar tissue instead of healthy liver tissue. "The authors found that the ADH1B 48His variant was overrepresented in patients with alcoholic liver cirrhosis and chronic alcoholic calcific pancreatitis." (PMID 28714907, 2017). "ADH1B allele was associated with a reduction in alcohol consumption and might be an important protective factor for alcoholic liver cirrhosis, especially for Asians." (PMID 27450204, 2016).
bladder cancer (3 papers, 2020 to 2022). "The present null result may, therefore, suggest the need for future studies that investigate bladder cancer risk associated with alcohol consumption stratified by the ALDH2 and ADH1B polymorphisms in East Asians." (PMID 31204364, 2020).
colon cancer (3 papers, 2017 to 2023). "This regulation was lost in colon cancer due to a dramatic decrease in the expression of ADH1B." (PMID 37185128, 2023).
depression (3 papers, 2020 to 2023). "A total of nine polygenic traits and genotypes are investigated in this study, including PGSs of height, body mass index, depression, time discounting, reproduction, educational attainment, risk preference, ADH1B rs1229984 and ALDH2 rs671." (PMID 34457340, 2021). "This study aims to help fill the literature gap on the causal relationship between alcohol use and depression by using genetic variants of ALDH2 rs671 and ADH1B rs1229984 to instrument for alcohol use in the Mendelian randomization (MR) framework." (PMID 33193720, 2020). "We aim to help fill the literature gap on the causal effect of alcohol use on depression by using genetic instruments of ALDH2 rs671 and ADH1B rs1229984 in the Mendelian randomization (MR) framework." (PMID 33193720, 2020).
hypopharyngeal cancer (3 papers, 2017 to 2023). Carcinoma, predominantly squamous cell, arising from the epithelial cells of the hypopharynx. "Alcohol dehydrogenase 1B (ADH1B) single‐nucleotide polymorphism (SNP) important in the susceptibility of oro‐ and hypopharyngeal cancer." (PMID 37706329, 2023).
melanoma (3 papers, 2022 to 2024). A malignant, usually aggressive tumor composed of atypical, neoplastic melanocytes. "Another study confirmed the downregulation (~9-fold) of ADH1B in human primary melanoma samples compared to normal skin tissues by analyzing two of the three datasets (GSE15605 and GSE46517) and another dataset GDS1375." (PMID 36831600, 2023). "Their Cox regression analysis revealed that ADH1B is an independent prognostic factor in human melanoma." (PMID 36831600, 2023). "After literature research, we chose 6 hub genes: ALDH2, ADH1B, ALDH3A2, DPT, EPHX2, and GATM, which were rarely reported in melanoma as the object of this research to explore their accuracy in the diagnosis and prediction of melanoma." (PMID 38378847, 2024). "Taken together, ALDH2, ADH1B, ALDH3A2, DPT, EPHX2, and GATM are potential biomarkers of melanoma, which have high prediction values for melanoma." (PMID 38378847, 2024). "When compared to normal skin tissues, primary melanoma tissues showed reduced ADH1B, CYP2E1, and CAT gene expression in at least two of three datasets (left), consistent with previous observations for ADH1B." (PMID 36831600, 2023). "Among them, only PDZD2, NPY1R and ADH1B have not been reported in melanoma studies, and EMP3 has only been reported in uveal melanoma." (PMID 35433681, 2022).
alcohol intolerance (2 papers, 2023 to 2025). "A key factor influencing alcohol use among Asians is alcohol intolerance, caused by the ALDH2*2 (rs671), ADH1B*2 (rs1229984), and other alleles for alcohol metabolism." (PMID 41302551, 2025). "Both rs671 (G > A) in ALDH2 and rs1229984 (T > C) in ADH1B were examined as markers of alcohol intolerance." (PMID 38328521, 2023). "One limitation is that our sample included Asian students from diverse backgrounds rather than being limited to East Asian ancestry, which is more strongly associated with genetic variants linked to alcohol intolerance and flushing [e.g., ALDH2*2 (rs671) and ADH1B*2 (rs1229984)]." (PMID 41302551, 2025).
allergies (2 papers, 2014 to 2024). "Our MR results, obtained by using ALDH2 rs671 and ADH1B rs1229984 as genetic IVs, showed that alcohol consumption can lead to allergic symptoms in Chinese females, and the observed negative or null association between drinking and allergy in conventional linear regression models is not causal." (PMID 39838956, 2024).
breast tumors (2 papers, 2009 to 2017). "Another study noted decreased protein levels of ADH1B in breast tumors, postulating the inability to oxidize the hydroxyl group of retinol blocks the production of retinoic acid, a molecule that helps maintain epithelial cells in their differentiated state." (PMID 19946374, 2009).